SLC38A6 (solute carrier family 38 member 6)
Description:
Amino acid transporter with an apparent selectivity for L-glutamine and L-glutamate. May facilitate glutamine uptake in excitatory neurons. The transport mechanism remains to be elucidated.
Synonyms: NAT-1; SNAT6
Tractability: Antibody: UniProt places it where antibodies can reach, with medium confidence; UniProt predicts a signal peptide or a membrane-spanning region; its Gene Ontology location is reachable by antibodies, with medium confidence; the Human Protein Atlas places it where antibodies can reach.
Gene: Protein-coding gene on chromosome 14 (60,981,114 to 61,114,316, forward strand). Ensembl gene ENSG00000139974.
Subcellular location: Cell membrane; Synapse
Subcellular location (Human Protein Atlas): Cell Junctions; Microtubules; Plasma membrane
Gene Ontology:
Molecular function: protein binding; L-glutamate transmembrane transporter activity; L-glutamine transmembrane transporter activity
Biological process: amino acid transmembrane transport; glutamine transport; L-glutamate transmembrane transport
Cellular component: plasma membrane; synapse
Genetic constraint (gnomAD): Loss-of-function variants: 37 observed, 31.33 expected, observed/expected ratio (o/e) 1.18, 90% interval 0.91 to 1.55. The upper end of that interval is the gene's LOEUF score, 1.55, which puts it in group 6 of 6, group 1 being the genes least tolerant of losing a copy. Missense variants: 363 observed, 342.02 expected, observed/expected ratio (o/e) 1.06, 90% interval 0.97 to 1.16. Synonymous variants: 114 observed, 118.45 expected, observed/expected ratio (o/e) 0.96, 90% interval 0.83 to 1.12.
Homologues: Orthologues: macaque SLC38A6 (96% identical), chimpanzee SLC38A6 (95% identical), pig SLC38A6 (89% identical), guinea pig SLC38A6 (88% identical), rabbit SLC38A6 (87% identical), dog SLC38A6 (86% identical), rat Slc38a6 (83% identical), mouse Slc38a6 (83% identical), tropical clawed frog slc38a6 (68% identical), zebrafish slc38a6 (54% identical), Drosophila melanogaster CG32079 (18% identical), Caenorhabditis elegans slc-36.3 (16% identical), and 11 more. Paralogues in human: SLC38A4 (48% identical), SLC38A3 (47% identical), SLC38A2 (45% identical), SLC38A5 (43% identical), SLC38A1 (41% identical), SLC38A11 (23% identical), SLC38A7 (23% identical), SLC32A1 (22% identical), SLC38A10 (21% identical), SLC36A2 (20% identical), SLC36A4 (20% identical), SLC38A9 (20% identical), and 3 more.
Diseases named in the same sentence as SLC38A6 in open-access papers:
SLC38A6 is named in the same sentence as 14 diseases in open-access papers, as found by Europe PMC text mining. Sharing a sentence is not in itself a finding about the gene and the disease. The quoted sentences say what the papers report.
gastric cancer (2 papers, 2022 to 2025). A primary or metastatic malignant neoplasm involving the stomach. "For example, Circ_0110940 exerts a pro-proliferative effect in gastric cancer through the miR-1178-3p/SLC38A6 axis." (PMID 41002382, 2025). "In our study, upregulation of SLC38A6 in gastric cancer cells was verified after we identified that it exhibited higher expression in gastric cancer tissues than control tissues based on bioinformatics analysis." (PMID 35813866, 2022). "Second, expression of circ_0110940/miR-1178-3p/SLC38A6 in human gastric cancer tissues needs to be validated." (PMID 35813866, 2022). "Moreover, since gastric cancer exhibits high metastasis, the effects of circ_0110940/miR-1178-3p/SLC38A6 on cell migration and invasion deserve further exploration." (PMID 35813866, 2022). "Furthermore, SLC38A6 rescued the effects of circ_0110940 knockdown on gastric cancer cell proliferation and apoptosis." (PMID 35813866, 2022). "In conclusion, circ_0110940 promoted cell proliferative ability and inhibited cell apoptotic capacity in gastric cancer cells via the miR-1178-3p/SLC38A6 axis, which may provide a basis for the targeted therapy of gastric cancer." (PMID 35813866, 2022). "In conclusion, circ_0110940 exerted an antiapoptotic and pro-proliferative effect in gastric cancer cells via the miR-1178-3p/SLC38A6 axis, which may provide basis for the targeted therapy of gastric cancer." (PMID 35813866, 2022). "SLC38A6 serves as a direct target of miR-1178-3p in gastric cancer cells." (PMID 35813866, 2022). "We further revealed the upregulation of SLC38A6 in AGS and MKN45 gastric cancer cells." (PMID 35813866, 2022).
hepatocellular carcinoma (2 papers, 2023 to 2025). A malignant tumor that arises from hepatocytes. "The gene SLC38A6 is involved in glutamine transport and the silencing of the gene resulted in the inhibition of cell cycle progression and cell viability in a hepatocellular cancer cell line." (PMID 36675023, 2023).
bacterial pneumonia (1 paper, 2023). Acute infection of the lung parenchyma caused by bacteria (e.g., Streptococcus pneumoniae, Haemophilus influenzae, Chlamydia pneumoniae, Mycoplasma pneumoniae, and Legionella pneumophila). "Through our study, we conclude that the expression of SLC38A6 is enhanced in PBMCs of patients with bacterial pneumonia and in the mice model of sepsis-associated pulmonary inflammation." (PMID 36707853, 2023). "In addition, these findings indicate that SLC38A6 can become a pharmacologically manageable molecular target for developing new treatment strategies for bacterial pneumonia and sepsis-associated pulmonary inflammation." (PMID 36707853, 2023). "To study pulmonary inflammation, we collected PBMC samples from patients with bacterial pneumonia and control patients, found increased Slc38a6 expression, and the upregulated expression level in PBMCs was positively correlated with the increasing number of monocytes." (PMID 36707853, 2023). "In addition, the SLC38A6 expression level was positively correlated with the number of monocytes (R2 = 0.27, p = 0.02) and WBC (R2 = 0.49, p = 0.01), suggesting that the overexpressed SLC38A6 may participate in bacterial pneumonia." (PMID 36707853, 2023).
pancreatic adenocarcinoma (1 paper, 2022). "A previous study revealed the upregulation of SLC38A6 in pancreatic adenocarcinoma." (PMID 35813866, 2022).
pneumonia (1 paper, 2023). An acute, acute and chronic, or chronic inflammation focally or diffusely affecting the lung parenchyma, caused by an infection in one or both of the lungs (by bacteria, viruses, fungi, or mycoplasma.). "In this study, pneumonia patient blood was found up-regulated SLC38A6 expression, which correlated with monocytes number and white blood cell number." (PMID 36707853, 2023).
Sepsis (1 paper, 2023). Sepsis is defined as life-threatening organ dysfunction caused by a dysregulated host response to infection. "We used LPS induced sepsis-associated pulmonary inflammation model, which is more in line with our research plan and more conducive to the study of the function of SLC38A6." (PMID 36707853, 2023). "For understanding the protentional Slc38a6 function, we focused our research on sepsis-associated pulmonary inflammation." (PMID 36707853, 2023). "Deficiency of SLC38A6 can reduce the severity and inflammation of sepsis-associated pulmonary inflammation in mice, which mainly depends on the participation of macrophages." (PMID 36707853, 2023). "Here, we demonstrate that up-regulated SLC38A6 plays an important role in sepsis-associated pulmonary inflammation through monocytes/macrophages." (PMID 36707853, 2023). "Through systemic deletion of Slc38a6, mice could alleviate the sepsis-associated pulmonary inflammation, mainly by reducing cytokine storm and activated macrophages, monocytes or neutrophils." (PMID 36707853, 2023). "We have found a new solute carrier called SLC38A6, which is essential for sepsis-associated pulmonary inflammation, SLC38A6 may mediate inflammation by directly participating in the maintenance of IL-1β in macrophages." (PMID 36707853, 2023). "Our results show that not only the systematic Slc38a6 knock-out but also Slc38a6 specific knock-out in LyzCRE cells could ameliorate LPS induced sepsis-associated pulmonary inflammation severity, and decrease inflammatory cytokines, such as TNF-α and IL-1β." (PMID 36707853, 2023). "We stimulated SLC38A6+/− and SLC38A6−/− mice with LPS, the main pathogenic factor of GNB, to mimic sepsis-associated pulmonary inflammation." (PMID 36707853, 2023).
stomach adenocarcinoma (1 paper, 2022). "SLC38A6 is revealed to be upregulated in 408 stomach adenocarcinoma tissues compared with 36 normal tissues based on GEPIA database." (PMID 35813866, 2022).
Tremor (1 paper, 2025). An unintentional, oscillating to-and-fro muscle movement about a joint axis. "In conclusion, we identified variants in SLC38A6 that contribute ~8.35% to ET, generated mouse models displaying tremor, and delineated cerebellar cellular abnormalities and potential mechanisms underlying ET etiology." (PMID 40931016, 2025). "Further characterization revealed that the SLC38A6 variants significantly altered cellular arginine homeostasis, resulting in functional and morphological changes in cerebellar cells, including PC degeneration and loss, as well as tremor phenotypes." (PMID 40931016, 2025). "In addition, both Slc38a6-/- and Slc38a6PC-/- mice developed tremors and pathological changes, confirming the critical role of Slc38a6 deficiency in the PC in mediating tremor." (PMID 40931016, 2025). "Furthermore, heterozygous Slc38a6 deletion (Slc38a6+/-) and PC-specific Slc38a6 deletion (Slc38a6PC-/-) mice also displayed tremor and PC abnormalities similar to those found in Slc38a6-/- mice." (PMID 40931016, 2025). "Since Slc38a6-/- mice developed tremors, we investigated whether Slc38a6-/- mice exhibited cerebellar morphological changes similar to those found in ET patients." (PMID 40931016, 2025). "IV:12 did not carry any of the variants of SLC38A6 but resulted in mild tremor." (PMID 40931016, 2025).
cancer (2 papers, 2022 to 2024). A tumor composed of atypical neoplastic, often pleomorphic cells that invade other tissues. "Several SLC38 isoforms have previously been linked to cell proliferation, invasion, migration and/or angiogenesis, including SLC38A2, SLC38A3, SLC38A6 and SLC38A7, supporting their involvement in cancer progression." (PMID 38254895, 2024).
tumor (2 papers, 2023 to 2024). "SLC38A6 and SLC38A7 expressions in tumor tissue sections were higher than those in normal tissue sections." (PMID 39357829, 2024). "By analyzing TCGA data in the GEPIA database, we found that the expression levels of multiple SLC38A family members (including SLC38A2, SLC38A4, SLC38A5, SLC38A6, SLC38A7, SLC38A8, SLC38A9, and SLC38A10) were significantly upregulated in GC tumor tissues." (PMID 36918802, 2023).
inflammation (1 paper, 2023). Aberrant reaction of the microcirculation characterized by movement of fluid and leukocytes from the blood into extravascular tissues. "Taken together, our data firstly showed that an amino acid transporter Slc38a6 is involved in pulmonary inflammation via monocytes/macrophages activation dependent on Tlr4 signaling and could be a potential target for future development of therapeutic targets for pulmonary inflammation." (PMID 36707853, 2023).
SLC38A6 also shares sentences with these, for which no sentence is quoted: bacterial infection (1 paper); essential tremor (1); metastatic tumors (1).